MSTN (myostatin)
Diseases named in the same sentence as MSTN in open-access papers (continued):
Sharing a sentence is not in itself a finding about the gene and the disease.
Obesity (continued). "Although previous studies have suggested that myostatin inhibition can reduce fat, its heterogeneous effects on fat storage and metabolism warrant further investigation, particularly in the context of obesity and metabolic syndrome." (PMID 41439973, 2025). "Expanding the scope of clinical trials targeting obesity, diabetes, and metabolic syndrome is critical for determining MSTN inhibition’s effectiveness in treating these disorders." (PMID 39340593, 2025). "Deletion of myostatin in mice also resulted in decreased fat mass, increased muscle mass, improved insulin sensitivity and resistance to diet‐induced obesity." (PMID 39764565, 2025). "Circulating MSTN levels and muscle MSTN expression are typically higher in people with obesity and T2D than in healthy people." (PMID 40171198, 2025). "The increased MSTN levels in obesity, insulin resistance, and diabetes suggest that MSTN-targeted inhibitors can improve metabolic function and promote weight loss in obese individuals." (PMID 39340593, 2025). "Concordantly, the skeletal muscle mRNA and protein expression and circulating abundance of myostatin are reportedly elevated with obesity and correlate with body mass index (BMI)." (PMID 37801203, 2024). "Since its discovery, myostatin has been recognized as a potential mediator of muscle atrophy in various pathological conditions, including obesity and T2DM." (PMID 38673892, 2024). "Especially, myostatin acts as a negative regulator of skeletal muscle mass and frequently increases in obesity." (PMID 38474229, 2024). "We add to the literature by measuring fasting serum myostatin levels by LC–MS/MS, and demonstrating that the associations are independent of BMI, VAT, ALM, and sex, in otherwise healthy adults with overweight/obesity." (PMID 39261976, 2024). "For instance, elevated MSTN levels have been observed in individuals with obesity and insulin resistance, implicating it in the pathophysiology of metabolic syndrome." (PMID 38889010, 2024). "Neither chronic exposure to obese SAT secretome nor acute elevation of fatty acid availability (which induced insulin resistance) replicated the obesity-mediated upregulation of myostatin mRNA expression in vitro." (PMID 37801203, 2024). "This study addresses these limitations by including only healthy adults with overweight/obesity and measuring serum myostatin levels by liquid chromatography tandem mass spectrometry (LC–MS/MS)." (PMID 39261976, 2024). "Serum myostatin increases in obesity, positively correlates with insulin resistance indices, and serves as a significant predictor of fat accumulation in non-obese patients with non-alcoholic fatty liver disease." (PMID 39562792, 2024). "In this pilot study, the acute practice of the novel RVT improved the ISF glucose concentration, FGF21 and myostatin levels, and muscle stiffness and fatigue in middle-aged and older adults with obesity." (PMID 36981616, 2023). "The mRNA levels of MSTN and its receptor ActRIIb were increased by more than 50-to 100-fold in subcutaneous and visceral fat of ob/ob mice (a mouse model of obesity) compared with wild-type mice." (PMID 37288303, 2023). "Moreover, high-fat feeding could significantly increase the body weight and the expression of MSTN in muscle of high-fat diet induced obesity susceptible mice models, but the expression of MSTN in muscle of high-fat diet induced obesity resistant mice does not change significantly." (PMID 37288303, 2023). "Here, we will discuss the role of the two most studied PGC-1α-dependent myokines, irisin and myostatin, in the deterioration of muscle structure and function in obesity." (PMID 37374197, 2023). "Myokines affecting sarcopenic obesity include IL-6, IL-10, IL-15, myostatin, insulin-like growth factor (IGF-1), irisin, FGF-21, and leukemia inhibitory factor (LIF)." (PMID 35250869, 2022).
Obesity (continued). "These events appear to affect myokines that are effective in sarcopenic obesity such as IL-6, IL-10, IL-15, myostatin, insulin-like growth factor (IGF-1), irisin, and fibroblast growth factor-21 (FGF-21)." (PMID 35250869, 2022). "Studies have shown that myostatin is elevated in humans with obesity due to an overproduction of myostatin in skeletal muscle cells." (PMID 35631274, 2022). "Increased circulating and muscle myostatin concentrations have been reported in adults with extreme obesity (i.e. BMI of 49 kg/m2) and BMI is strongly correlated with muscle myostatin concentrations." (PMID 35287731, 2022). "MSTN is upregulated in obesity animal models of obesity, and elevated myostatin levels have been observed in obesity in humans." (PMID 35011721, 2022). "Myostatin (MSTN), a myokine known to inhibit skeletal muscle growth, has been associated with the development of obesity and IR." (PMID 35273574, 2022). "Conversely, disruption of the myostatin gene in a high-fat diet mouse model prevents diet-induced obesity and insulin resistance." (PMID 35287731, 2022). "Myostatin is upregulated in animal models of obesity, and elevated myostatin levels have been observed in obese subjects." (PMID 36359757, 2022). "The relationship between elevated myostatin and obesity has been demonstrated in both rodent and human studies." (PMID 35287731, 2022). "In conclusion, myostatin concentrations rise with age and pubertal development in young male patients with severe obesity." (PMID 35631274, 2022). "The introduction of MSTN protein-like molecules and the manipulation of endogenous MSTN levels also offer potential means for preventing or treating metabolic ailments like muscle wasting, type 2 diabetes, and obesity." (PMID 34440852, 2021). "Elevated myostatin levels were registered in pathological conditions characteristic of the metabolic deregulations such as obesity, T2DM and aging." (PMID 33782504, 2021). "Serum adiponectin levels in male patients with obesity were significantly lower than those in female patients with obesity, while serum myostatin levels in male patients with obesity were significantly higher than those in female patients with obesity." (PMID 33465151, 2021). "Deletion of myostatin has also been suggested to result in the activation of beige adipocytes, thermogenic fat cells with anti-obesity and anti-diabetes properties." (PMID 33220490, 2021). "Myostatin null mice have increased skeletal muscle mass and are protected from obesity and its sequelae." (PMID 33220490, 2021). "Myostatin levels have been reported to be lower in patients with severe obesity; furthermore, levels are higher in men than in women." (PMID 33465151, 2021). "For example, Akt1 overexpression in skeletal muscle can stimulate hypertrophy of glycolytic fibers, as is seen in myostatin-null muscle, and concomitant robust protection from obesity." (PMID 33220490, 2021). "In our study, patients with obesity had a median serum adiponectin level of 2.9 μg/mL and a serum myostatin level of 2398.4 pg/mL." (PMID 33465151, 2021). "Several lines of evidence suggest that obesity poses a threat to skeletal muscle health via myostatin." (PMID 34641817, 2021). "Myostatin null mice, in addition to remarkable skeletal muscle hypertrophy, are protected from obesity and metabolic dysfunction and demonstrate browning of the white fat." (PMID 33220490, 2021). "MSTN is also highly expressed in adipose tissues and is viewed as a potential target in obesity and type 2 diabetes mellitus because of the prominent role it plays in insulin-mediated glucose disposal and in determining the metabolic rate of SM." (PMID 34440852, 2021). "The results of our study have clinical implications towards understanding the effects of circulating adiponectin and myostatin levels on body composition and metabolic parameters in patients with obesity." (PMID 33465151, 2021).
Obesity (continued). "Plasma levels of adiponectin can be reduced with the increase in pro-inflammatory cytokines such as TNF-α and IL-6, present in obesity, in addition to the levels of myostatin, a myokine that can elevate the adipose tissue mass." (PMID 33807959, 2021). "This study aims to evaluate serum adiponectin and myostatin levels in patients with obesity and identify independent factors using body composition and metabolic factors." (PMID 33465151, 2021). "Blocking MSTN activity by MSTN propeptide overexpression prevents the development of diet-induced obesity and insulin resistance in transgenic animals." (PMID 32316589, 2020). "The role of Myostatin in adipogenesis and diet-induced obesity is of interest in current studies since previous studies showed a suppression of body fat accumulation in myostatin-deficient mice; however, this effect seems to be context-dependent." (PMID 32784522, 2020). "Previous studies extensively addressed the role of Myostatin in obesity as well as caloric restriction." (PMID 32784522, 2020). "To study this question, we compared lymphatic function in genetically obesity-resistant [myostatin (MSTN) knockout and BALB/c mice] and obesity-prone (C57BL/6J) mice that were fed on a HFD for prolonged periods of time." (PMID 32499718, 2020). "Myostatin and follistatin levels were slightly higher in women with obesity compared with normal-weight subjects." (PMID 32316563, 2020). "Regarding myokines, the irisin level was lower (p < 0.001), while follistatin and myostatin levels were higher (p < 0.05), in patients with obesity compared with controls." (PMID 32316563, 2020). "The inhibition of MSTN induced by gene manipulation or neutralizing antibodies improves sarcopenic obesity by increasing skeletal muscle mass and improving glucose homeostasis." (PMID 30717377, 2019). "For example, increased expression of myostatin (MSTN), a secreted anabolic inhibitor of muscle growth and development, has been associated with obesity and insulin resistance." (PMID 30717377, 2019). "Inhibition of myostatin signaling has also been shown to have beneficial metabolic effects in obesity and diabetes, including enhanced glucose tolerance, improved brown adipogenesis, and reduced fat mass." (PMID 30765322, 2019). "For example, MSTN gene knockout in animals mainly leads to reduced fat mass and resistance to diet-induced obesity." (PMID 28344633, 2017). "By contrast, the inhibition of MSTN signaling in skeletal muscle increased lean mass and decreased fat mass on standard and high-fat diets, as well as resistance to diet-induced obesity." (PMID 28344633, 2017). "Adipose tissue-specific MSTN overexpression increases the metabolic rate and resistance to diet-induced obesity." (PMID 28344633, 2017). "It is thus highly possible that the inhibition of myostatin activity can be used as a new strategy to treat obesity." (PMID 28432282, 2017). "In transgenic myostatin propeptide mice where myostatin activity is inhibited, food-induced obesity was significantly reduced." (PMID 28432282, 2017). "Specific overexpression of MSTN in adipose tissue increases the metabolic rate and resistance to diet-induced obesity." (PMID 28344633, 2017). "Exercise diminishes myostatin expression, whereas obesity augments myostatin levels in muscle and serum." (PMID 28025491, 2016). "It was proposed that inhibition of the myostatin pathway in mice results in resistance to develop high-fat diet-induced and genetic obesity, suggesting a potential role for myostatin inhibition in the treatment of obesity and diabetes." (PMID 26644908, 2015). "Recent reports on Mstn knock out (Mstn−/−) mice or treatment with myostatin antagonists (e.g. soluble activin type IIB receptor) showed resistance to develop obesity in response to high-fat diet." (PMID 26644908, 2015).
Obesity (continued). "Research has evaluated myostatin inhibition as a strategy to prevent the development of obesity and concluded in some cases that it offers a protective mechanism against a high-fat diet." (PMID 26644908, 2015). "This supports the use of myostatin blockade for the treatment of metabolic diseases such as type II diabetes or for obesity." (PMID 24760516, 2014). "Genetic manipulations disrupting myostatin signaling, such as expressing a dominant negative form of the myostatin receptor in satellite cells in an obesity model, will help to answer this question." (PMID 24381559, 2013). "Intriguingly, the inhibition of myostatin induced by gene manipulation or neutralizing antibody ameliorates sarcopenic obesity via increased skeletal muscle mass and improved glucose homeostasis." (PMID 23690769, 2013). "In the multivariate analysis muscle myostatin mRNA content was predicted by age and plasma IL-6, when adjusting for insulin resistance, plasma triglycerides and obesity." (PMID 22615949, 2012). "The finding that myostatin knock-out mice are protected against obesity-induced insulin resistance as measured by a hyperinsulemeamic clamp suggests an effect of myostatin on insulin-mediated glucose uptake." (PMID 22615949, 2012). "Future research on the potential anti-obesity effect of inhibiting myostatin activity should evaluate the possibility that subcutaneous adipose tissue is affected more than intra-abdominal adipose tissue after prolonged high-fat feeding." (PMID 21390326, 2011). "Treatment of mice that are obese due to different genetic or dietary causes with myostatin antagonists will clarify which, if any, specific types of obesity are rescued by postnatal inhibition of myostatin." (PMID 19295913, 2009). "It has been suggested that myostatin plays a direct role in the deterioration of the skeletal muscle in states of obesity and insulin resistance." (PMID 19730740, 2009). "FST and MSTN secretion are both increased by primary myotubes from people with obesity and T2D, suggesting that muscle may contribute to increased circulating FST levels." (PMID 40171198, 2025). "SRK-439 is a selective myostatin inhibitor designed to treat obesity." (PMID 40104296, 2025). "Imbalances in myokines, such as MSTN and irisin, together with changes in adipokine levels, may promote a sarcopenic-obesity phenotype." (PMID 41303309, 2025). "Additionally, adipose tissue can release substances, such as adipokines, that impede myogenesis, and obesity is correlated with increased levels of myostatin, a muscle growth inhibitor." (PMID 40718355, 2025). "Furthermore, regular exercise has been shown to reduce myostatin transcript levels in the skeletal muscle of individuals with obesity and impaired glycemic control." (PMID 39337980, 2024). "In conclusion, our data suggest that higher serum myostatin levels are associated with lower insulin sensitivity in otherwise healthy adults, age 20–65 years, with overweight/obesity, independent of other risk factors for insulin resistance." (PMID 39261976, 2024). "Western diet-induced obesity and T2DM may be linked to muscle atrophy through upregulation of myostatin and subsequent increase in the ubiquitin and autophagy systems." (PMID 38673892, 2024). "Furthermore, specific overexpression of MSTN in adipose tissue has been demonstrated to increase the metabolic rate and resistance to diet-induced obesity (DIO)." (PMID 38889010, 2024). "Furthermore, IR promotes skeletal muscle reduction by increasing the amount of myostatin and aggravating obesity by inhibiting the decomposition of visceral fat." (PMID 38628269, 2024). "Thus, we provide novel evidence suggesting a dissociation between skeletal muscle insulin resistance and the upregulation of myostatin mRNA expression in human obesity." (PMID 37801203, 2024).
Obesity (continued). "The capacity for MyoD to upregulate myostatin provides a potential mechanistic link between their concurrent upregulation in the AEA group, whereby the initial upregulation of MyoD in ageing with obesity may precede and promote the upregulation of myostatin." (PMID 37801203, 2024). "Thus, in vitro experiments were undertaken to isolate the effects of cross-talk between SAT, constituting the largest adipose compartment in obesity, and skeletal muscle on myostatin mRNA expression." (PMID 37801203, 2024). "Nutraceuticals such as green cardamom, which can inhibit myostatin secretion, promote irisin secretion, or treat obesity, may also be a possible aid in managing SO." (PMID 37686886, 2023). "Furthermore, intervention with the MSTN antagonist sActRIIB in wild-type HFD-fed mice significantly reduced obesity in mice." (PMID 37288303, 2023). "However, in future studies, the molecular mechanism of MSTN in obesity needs to be further revealed, which is conducive to the development of anti-obesity drugs targeting MSTN." (PMID 37288303, 2023). "For instance, it was demonstrated that the inhibition of myostatin was able to decelerate the development of insulin resistance and obesity in mice fed a high-fat diet, possibly due to the intensification of lipolysis and mitochondrial lipid oxidation in liver and adipose tissue." (PMID 37374197, 2023). "Our results showed that Rb1 may ameliorate obesity in part through the MSTN/FNDC5 signalling pathway." (PMID 35639355, 2022). "Taken together, these results suggest that in addition to pharmacological and surgical methods, the DASH diet maybe a potential strategy to reduce myostatin levels with concurrent parallel changes in adiposity that may in-turn benefit individulas with obesity." (PMID 35287731, 2022). "Furthermore, it has been demonstrated that the observed differences in serum levels are likely due to the overproduction of MSTN from skeletal muscle in obesity." (PMID 35273574, 2022). "Myostatin positively and follistatin negatively correlated with age and pubertal (Tanner) stage, but none of the investigated myokines/hepatokines correlated with the BMI within this group with severe obesity." (PMID 35631274, 2022). "Serum myostatin is upregulated in obesity and correlates with insulin resistance in humans." (PMID 36552772, 2022). "Many studies have suggested that MSTN has a substantial impact on metabolism and may contribute to the development of obesity and diabetes." (PMID 35812316, 2022). "This could potentially exacerbate the metabolic effects of sarcopenic obesity given the decreased glucose uptake resulting from decreased muscle mass heightened by the inhibitory action of myostatin on insulin sensitivity." (PMID 35287731, 2022). "In animals, MSTN-knockout typically reduces fat mass and resistance to diet-induced obesity." (PMID 36324508, 2022). "There are some potential and emerging treatments for SO, for instance, pharmacological interventions (testosterone supplementation, selective androgen receptor modulators, myostatin inhibitors, and anti-obesity drugs), electrical acupuncture and whole-body electromyostimulation, and A2B agonist." (PMID 35371597, 2022). "This evidence supports the hypothesis that obesity leads to an increase in myostatin, which impairs skeletal muscle health." (PMID 34641817, 2021). "Our findings suggest that therapeutically inhibiting myostatin could have broad benefits in the large population of patients with obesity and metabolic syndrome." (PMID 33220490, 2021). "However, we show in both male and female mice that beige fat activation is dispensable for the protection from obesity, glucose intolerance, insulin resistance, and hepatic steatosis mediated by myostatin deletion." (PMID 33220490, 2021).